VDR (vitamin D receptor)
Diseases named in the same sentence as VDR in open-access papers (continued):
Sharing a sentence is not in itself a finding about the gene and the disease.
diabetes (continued). "Vitamin D receptor (VDR) gene polymorphisms are possibly involved in the development of type 1 diabetes mellitus (T1DM)." (PMID 24603699, 2014). "A study reported gender-specific association of vitamin D receptor polymorphism which has significant effect on diabetes." (PMID 25485770, 2014). "A few studies have demonstrated that VDR polymorphisms were related to obesity, diabetes, insulin sensitivity and insulin secretion." (PMID 25106919, 2014). "Recently, the relationship between polymorphisms of VDR, especially FokI and TaqI, and susceptibility to several diseases associated with inflammation such as diabetes, autoimmune diseases, and tuberculosis has been shown." (PMID 23984350, 2013). "Li Hui-Min et al8 reported that the prevalence of VDR gene genotype frequencies and allele frequencies in patients with type 2 diabetes mellitus was significantly different from that in control subjects." (PMID 24353633, 2013). "In the same study, bb genotype of VDR BsmI polymorphism was associated with insulin resistance in subjects with diabetes." (PMID 22347618, 2012). "The association of BsmI VDR polymorphism with type 2 diabetes mellitus was analyzed in 293 patients considered at high risk for coronary artery disease." (PMID 23049672, 2011). "A significant association between VDR variants and susceptibility to several diseases including cancer, ulcerative colitis, metabolic syndrome and both types of diabetes has already been reported." (PMID 22114787, 2011). "There was some evidence of interaction between genetic polymorphisms and cardiovascular risk factors (ACE and high-density lipoprotein; VDR and diabetes) on brain volume decline." (PMID 22028967, 2011). "Evidence of associations between VDR variants and diabetes, a major CKD risk factor, and biochemical features of the metabolic syndrome have been reported." (PMID 23049672, 2011). "The large amount of positive genetic association data in a number of diseases such as osteoporosis, OA, diabetes, and cancer suggest functional consequences of VDR gene polymorphisms." (PMID 16507122, 2006). "A cross-sectional study further suggested that altered VDR polymorphism expression may contribute to microvascular complications in diabetes." (PMID 41438090, 2025). "Epidemiologic studies have demonstrated that VD supplementation can reduce the risk of diabetes progression in prediabetic individuals by up to 46%, while mechanistic research has revealed multiple cardioprotective pathways mediated through the vitamin D receptor (VDR)." (PMID 40746531, 2025). "The VDR genetic variants have been associated with a predisposition to metabolic bone diseases, chronic diseases, cancer, autoimmune diseases, cardiovascular alterations, rheumatic arthritis, and diabetes." (PMID 39859195, 2025). "Other factors may have a stronger influence on iPTH than VDR polymorphism, as diabetes, malnutrition, and medication are among them." (PMID 39335504, 2024). "Furthermore, VDR deficiency is associated with increased inflammation and deregulation in several inflammatory diseases, such as inflammatory bowel disease, sepsis, diabetes, and asthma." (PMID 37867510, 2023). "The interaction effect of genetic variants and cardiometabolic profiles may modify the relationship of vitamin D levels in prediabetic people, indicating different effect of VDR variants between diabetes and prediabetes." (PMID 37845735, 2023). "These medications may have affected the associations of VDR genotypes with biochemical profiles and diabetes complications." (PMID 36143273, 2022). "The association between VDR polymorphisms and type 2 diabetes mellitus (T2DM) remains inconclusive." (PMID 33567588, 2021). "Furthermore, several studies have shown that genetic polymorphisms in the VDR gene affect susceptibility to certain chronic diseases, such as diabetes and obesity." (PMID 34835935, 2021).
diabetes (continued). "Vitamin D receptor (VDR) gene polymorphisms may contribute to development of diabetes mellitus through calcium metabolism alteration and modulation of insulin secretion." (PMID 34903261, 2021). "Furthermore, genetic polymorphisms in the VDR gene affect the susceptibility to certain chronic diseases, such as diabetes and obesity." (PMID 34835935, 2021). "Yet, other studies have reported an association of VDR gene polymorphisms with PP and diabetes." (PMID 29669566, 2018). "In the recent years it has become evident that the pancreatic tissue, especially the β-cells express the vitamin D receptor(VDR) and variations in the genes controlling the vitamin D metabolism and expression of VDR have been implicated in the pathogenesis of diabetes(T1DM and type 2 DM)." (PMID 28882195, 2017). "Moreover, studies examining VDR polymorphisms reported significant associations with diabetes, arthritis, autoimmune diseases and hypertension." (PMID 27716192, 2016). "Vitamin D receptor (VDR) gene polymorphism have a role in diabetes mellitus pathogenesis." (PMID 26870091, 2015). "Notably, the VDR BsmI polymorphism, together with age, diabetes and calcitriol treatment, has been shown to strongly influence survival in hemodialysis patients, whereas the poly-A and FokI polymorphisms have not." (PMID 24618509, 2014). "Comparison of the various risk factors for PC (age, smoking, diabetes and chronic hepatitis B infection) and the frequency of VDR genotypes in PC patients may also be considered for further investigation." (PMID 23761840, 2013). "BsmI VDR polymorphisms have been associated with diabetes and fasting glucose." (PMID 23049672, 2011). "Increasing evidence shows that genetic variants of genes in the diabetes mellitus (DM) metabolic pathway, such as the vitamin D receptor (VDR) gene rs739837 polymorphism, increase the risk of DM susceptibility." (PMID 35526059, 2022). "Among numerous (>60) SNPs identified in the VDR gene were linked to the risk of several disease such as autoimmune disorders, including rheumatoid arthritis, systemic lupus erythematosus, inflammatory bowel disease, diabetes mellitus, multiple sclerosis, an autoimmune disease, cancer or Parkinson." (PMID 36233147, 2022). "Moreover, reported VDR polymorphisms may possibly be just markers of linkage disequilibrium with another gene, which may be responsible for the associations observed with type 2 diabetes mellitus." (PMID 33567588, 2021). "Also, there are some studies suggesting that VDR polymorphisms including ApaI may be associated with the development of diseases such as diabetes or metabolic syndrome." (PMID 33564343, 2021). "Our patient presented several risk factors (ESRD, female gender, history of obesity, diabetes mellitus, hyperparathyroidism, hyperphosphatemia and treatment with acenocoumarol and vitamin D receptor activator), so that we acted on those that could be modified pharmacologically." (PMID 30700922, 2018). "Moreover, VD deficiency and VDR has been reported to be associated with obesity and diabetes." (PMID 29112142, 2017). "A large amount of researches have demonstrated that vitamin D receptor (VDR) gene polymorphisms are associated with diabetic nephropathy (DN) risk in diabetes mellitus (DM) patients." (PMID 28851298, 2017). "Therefore, polymorphism of VDR gene is associated with type 2 diabetes mellitus in Han Chinese, and allele f may be a susceptible gene contributing to the development of type 2 diabetes mellitus in Han Chinese." (PMID 24353633, 2013). "It is generally accepted that VDR polymorphisms are linked to increased long-term mortality in the general population as evidenced by their high incidence in several chronic complications, such as coronary artery disease, osteoporosis, autoimmune disorders, diabetes, and cancer." (PMID 23717679, 2013).
diabetes (continued). "Moreover, vitamin D receptor (VDR) polymorphisms reportedly influence the expression and nuclear activation of the VDR, which has been considered to associate with different diseases such as malignant tumors and diabetes." (PMID 23717679, 2013). "A preclinical study suggested that diabetes reduces VDR expression in podocytes, impairing autophagy flux by down-regulating Atg3 in diabetic animal models, while the activation of VDR improves glomerular autophagy flux." (PMID 41141390, 2026). "In this study, experimental obese rat models were used to assess the impact of vitamin D and probiotic supplements on lipid profiles, inflammation, obesity, diabetes, VDR, and gut microbiota." (PMID 42255705, 2026). "Diabetes was the only predictor of placental VDR expression according to backwards and forward stepwise regression." (PMID 41007445, 2025). "In a model of diabetic heart injury, for instance, vitamin D reportedly attenuated diabetes-related cardiac damage and autophagy through VDR-mediated signaling and the consequent inhibition of FoxO1 translocation to the nucleus." (PMID 40564179, 2025). "Placental expression of the vitamin D receptor was higher in women with diabetes compared with controls, while serum vitamin D levels were similar in both groups." (PMID 41007445, 2025). "Some studies also showed that the vitamin D receptor (VDR) is involved in glucose metabolism regulation in both types of diabetes pathogenesis." (PMID 41536823, 2025). "There is increasing evidence that shows the crucial role of Vitamin D and VDR signaling in the etiopathogenesis of autoimmune diseases, such as multiple sclerosis (MS), rheumatoid arthritis (RA), diabetes mellitus (DM), and inflammatory bowel disease." (PMID 40243631, 2025). "Mounting evidence also has established a close relationship between VDR signaling and diabetes, as well as diabetic nephropathy and insulin resistance." (PMID 38318147, 2024). "A thorough understanding of how VDR SNPs affect the occurrence of osteoporosis and other diseases such as diabetes, cancer, and multiple sclerosis can be obtained by studying the prevalence of all SNPs throughout the nation." (PMID 39072539, 2024). "These TCM interventions range from single herbs to complex formulas, each providing unique insights into how VDR activity can be influenced to alleviate VDR-dependent diseases such as osteoporosis, cancer, psoriasis, diabetes, etc." (PMID 38318147, 2024). "Corneal nerve regeneration was significantly retarded by diabetes, VDR KO, and VDD, and it was accelerated following topical 1,25 Vit D and 24,25 Vit D administration." (PMID 38136625, 2023). "Patients with CKD are exposed to age-related and other risk factors for 25(OH)D deficiency, including female sex, adiposity, proteinuria, low physical activity, peritoneal dialysis, diabetes mellitus, and reduced vitamin D receptor (VDR)." (PMID 37351236, 2023). "Further studies are needed to determine the factors increasing the expression level of VDR, especially in the patients with diabetes, hypertension and cardiovascular disease." (PMID 37025056, 2023). "It has been reported that vitamin D receptor (VDR) changes involved in the pathogenesis of some chronic disorders such as diabetes, autoimmune diseases, nonalcoholic liver disease, cardiovascular disease(CVD), and cancer." (PMID 36742396, 2023). "We found that significance increased, when we adjusted the level of VDR gene expression with diabetes, hypertension and CVD." (PMID 37025056, 2023). "The rats of Ctrl VitDD and DM VitDD presented a significant reduction of VDR protein expression 24 weeks after diabetes induction when compared to Ctrl VitD and DM VitD groups (P = 0.0007)." (PMID 37391399, 2023). "VDR expression was lower in the patient with diabetes, hypertension and cardiovascular disease, significantly, p‐value = 0.002." (PMID 37025056, 2023).
diabetes (continued). "The aim of this study was to determine the effects of the VDR FokI, ApaI, TaqI, and BsmI genotypes on the lipid profile and major diabetes complications of T2DM patients of Jordanian Arabic origin." (PMID 36143273, 2022). "In this study, we investigated the influence of major VDR genotypes on lipid profiles and diabetes complications in a sample of T2DM patients of Jordanian Arabic origin." (PMID 36143273, 2022). "The four variants rs731236, rs7975232, rs1544410, and rs2228570 in the VDR gene are commonly related to metabolic disorders, such as diabetes, metabolic syndrome (MetS), and polycystic ovarian syndrome (PCOS)." (PMID 36046800, 2022). "The present study is not the first study conducted in Jordan to investigate the influence of VDR genotypes on diabetes." (PMID 36143273, 2022). "The same gene can perform different functions in the body, we found that the rs7975232 of VDR gene was related to the obesity and diabetes, it is also as the genetic makers of them." (PMID 34745225, 2021). "Numerous original studies and 4 published meta-analyses have reported the association between the Vitamin D receptor (VDR) BsmI, FokI, ApaI, and TaqI polymorphisms and type 2 diabetes mellitus (T2DM) risk." (PMID 34260520, 2021). "Recent genetic association studies showed that there are contradictory results on the relationship between vitamin D receptor (VDR) gene polymorphisms and type 1 diabetes mellitus (T1DM) risk in children." (PMID 34260558, 2021). "In females, a higher prevalence of diabetes mellites, use of statins, use of vitamin D receptor activators, and use of erythropoiesis-stimulating agents were associated with a low GNRI (<92)." (PMID 34445007, 2021). "Type 2 diabetes mellitus (T2DM) is a multifactorial disease associated with many genetic polymorphisms; among them is the FokI polymorphism in the vitamin D receptor (VDR) gene." (PMID 32823649, 2020). "Age, sex, dialysis vintage, history of diabetes mellitus and cardiovascular disease, and single-pool Kt/V for urea, use of vitamin D receptor activators and phosphate binders were also included in the multivariable-adjusted logistic regression analysis." (PMID 32238848, 2020). "Previously, human genetic studies linking vitamin D and VDR to diabetes mellitus suggested a potential role in pancreatic β-cell cycle and survival." (PMID 31387633, 2019). "As evidenced by the WB data, the VDR protein level in diabetes decreased 1.5-fold in comparison with the control (p = 0.009)." (PMID 29552033, 2018). "Maintaining a sufficient level of vitamin D in diabetes contributes to the normalization of impairments in the metabolism of vitamin D and VDR-mediated cellular signaling." (PMID 29552033, 2018). "Consistent with the diabetes-induced lowering of Vdr expression, there was a 1.8-fold decrease in the protein level of VDR in the bones (p = 0.0001)." (PMID 29552033, 2018). "Recently, the Diabetes Autoimmunity Study in the Young (DAISY) reported an interaction between a PTPN2 variant PTPN2 rs1893217 and a functional VDR variant VDR rs2228570 which is associated with progression of T1DM." (PMID 30246029, 2018). "Vitamin D/VDR helps in maintaining healthy intestinal microbiome, thus improving glucose homeostasis in diabetes." (PMID 30828578, 2018). "Our results revealed a diabetes-evoked decrease in bone tissue levels of VDR mRNA and protein that can reflect the impairment of osteoblast-mediated osteosynthesis." (PMID 29552033, 2018). "Type 1 diabetes mellitus is another type of diabetes in which HLA (human lymphocyte antigen), IR1R1 (interleukin-1 receptor type 1), CTLA-4, and VDR are some important genes studied in association with T1DM." (PMID 26587547, 2015). "We also investigated the association between either VDR FokI or BsmI polymorphim with co-morbidities observed in CKD patients, i.e., diabetes, hypertension, and LVH." (PMID 24618509, 2014).
diabetes (continued). "The role of vitamin D and involvement of the VDR in the pathogenesis of insulin-dependent diabetes mellitus (diabetes type 1) has been studied extensively." (PMID 25090635, 2014). "In type 1 diabetes mellitus (T1D), it plays an immunomodulatory role through the vitamin D receptor (VDR) present on pancreatic and immune cells." (PMID 23573085, 2013). "Certain vitamin D receptor (VDR) gene polymorphisms have also been associated with increased risk of AD, cardiovascular disease, and diabetes, and these, in turn, have been linked to WMLs." (PMID 22028967, 2011). "Univariate and multivariate linear regression analyses revealed that diabetes and gestational age were significantly associated with VDR expression (median), but none of the parameters were independent predictors." (PMID 41007445, 2025). "In STZ-induced diabetes models, VDR-knockout mice exacerbate renal injury compared to controls." (PMID 41438090, 2025). "Diabetes status, rather than BMI, gestational age, placental weight, or vitamin D levels, is the only variable independently associated with increased VDR expression." (PMID 41007445, 2025). "Metadichol is a novel nanolipid that treats diabetes by binding to the vitamin D receptor (VDR)." (PMID 40650120, 2025). "Stepwise regression revealed that diabetes was the only independent predictor of VDR expression." (PMID 41007445, 2025). "The vitamin D receptor (VDR) is expressed in insulin-responsive and immune cells, including pancreatic β-cells, adipocytes, skeletal muscle, and T lymphocytes, suggesting a potential regulatory role in diabetes pathophysiology." (PMID 40863099, 2025). "To clarify whether VDR regulates mitophagy in diabetes-induced renal fibrosis, we established STZ-induced diabetic mouse model." (PMID 38697845, 2024). "VDR is linked to many non-communicable diseases like osteoporosis, alopecia, diabetes, heart disease, and cancer." (PMID 38318147, 2024). "Taken together, the results with Drosophila provide additional insight into possible mechanisms for the anti-obesity and anti-diabetes effects of mifepristone observed in mice and humans, including the potential implication of Dhr96-related factors such as VDR and LXRa." (PMID 38127988, 2023). "Scientists have discovered more than 470 SNPs in the VDR gene, and thoroughly studied the role of four SNPs, rs2225870, rs1544410, rs7975232 and rs731236, in the pathogenesis of different diseases (cancer, diabetes, Parkinson’s disease, myocardial infarction and CAD)." (PMID 37760823, 2023). "Our study is one of the very few studies to measure the four single-nucleotide polymorphisms in the VDR gene including BsmI, FokI, TaqI and ApaI in a large sample of the UAE population with a high prevalence of overweight and obesity (76%), diabetes (17%) and hypertension (15%)." (PMID 37189820, 2023). "Previously, we showed the same effect of reducing VDR after the VD3 administration against the background of prednisolone load in various tissues and organs, including bone marrow and liver, as well as kidneys and liver in diabetes-associated VD3 deficiency." (PMID 37020845, 2023). "The association between vitamin D receptor VDR polymorphism and the risk of chronic diseases including obesity, hypertension, diabetes and other cardiovascular diseases therefore remains unclear." (PMID 37189820, 2023). "Collectively, these findings suggest that enhancing INGAP-PP-based treatment formulations for people with diabetes could potentially involve co-treatment with vitamin D receptor agonists." (PMID 37842306, 2023). "Lastly, the blood levels of vitamin D were not analyzed, which could have helped elucidate the correlations of VDR genotype with vitamin D levels, diabetes complications, and lipid profiles." (PMID 36143273, 2022). "Lipid profiles and diabetes complications were analyzed and correlated with VDR genotypes." (PMID 36143273, 2022).